RN7SKP11 (RN7SK pseudogene 11)
Gene: Miscellaneous RNA gene on chromosome 12 (96,427,200 to 96,427,486, reverse strand). Ensembl gene ENSG00000252827.
Homologues: Orthologues: chimpanzee 7SK (98% identical), guinea pig 7SK (42% identical), mouse Gm55779 (40% identical). Paralogues in human: RN7SKP193 (52% identical), RN7SKP203 (52% identical), 7SK (51% identical), RN7SKP90 (51% identical), RN7SKP246 (51% identical), RN7SKP134 (51% identical), RN7SKP176 (51% identical), RN7SKP255 (51% identical), RN7SKP50 (51% identical), RN7SKP47 (50% identical), RN7SKP80 (50% identical), RN7SKP131 (50% identical), and 284 more.